CXCR2 (C-X-C motif chemokine receptor 2)
Diseases named in the same sentence as CXCR2 in open-access papers (continued):
Sharing a sentence is not in itself a finding about the gene and the disease.
tumor (continued). "Subsequently, secretion of CXCR2 ligands by inflamed tumor cells promotes the accumulation of CXCR2+ TANs, which in turn inhibits the cytotoxic activity of CD8+ T cells and facilitates tumor progression." (PMID 39795864, 2024). "Tumor lysates from MDA-PCa-2b-CXCR1 (0.618 ± 0.013) xenografts displayed a ~40% decrease in VEGF expression relative to MDA-PCa-2b-CXCR2 (0.997 ± 0.110) and MDA-PCa-2b-Vec (1.000 ± 0.074)." (PMID 39766038, 2024). "Overall, the signalling induced by IL-8 on either CXCR1 or CXCR2 influences many aspects of tumour progression within the TME, providing promising targets for therapeutic interventions." (PMID 39199570, 2024). "Lastly, we investigated the tumor tissues and found that expression of ectopic CXCR2 significantly improved tumor-targeted infiltration and residence of T cells and reduced the presence of MDSCs and CXCR2 + macrophages in PDAC microenvironment." (PMID 38430267, 2024). "For instance, it has been showed that CAR-T cells overexpressing the IL-8 receptors CXCR1 or CXCR2 had better tumor infiltration and anti-tumor effects." (PMID 38622705, 2024). "Increased CXCR2 expression in tumor cells and myeloid cells is responsible for recruitment of MDSC to the tumor microenvironment, which promotes tumor progression." (PMID 38324085, 2024). "CXCR2, the receptor for CXCL3 and CXCL5, has been associated with promoting cellular processes such as tumor cell proliferation, migration, invasion, angiogenesis, lymphangiogenesis, and cellular senescence." (PMID 38365809, 2024). "Similar to the s.c. flank model, orthotopic MOC1 tumors exhibited high levels of CXCL1 expression in tumor cells and CXCR2 expression in CD45+ immune cells when evaluated by RNA in situ hybridization." (PMID 39639338, 2024). "C-X-C motif chemokine receptor 2 (CXCR2) has a role in tumor progression, lineage plasticity, and reduction of immune checkpoint inhibitor efficacy." (PMID 38324085, 2024). "This idea was supported by other studies that have shown that CXCR2-modified cells improved tumor infiltration capability." (PMID 38201305, 2024). "The in vivo experiments also verified that the Fn-induced pro-tumor effect was attenuated after blocking the CXCL2 receptor (CXCR2)." (PMID 38637499, 2024). "We also analyzed the expression of CXCR2 in xenografts as well as in the blood and spleen of the tumor-bearing animals." (PMID 39630608, 2024). "CAR-T cells expressing CXCR2 appeared more efficacious at tumor homing than CXCR1-expressing CAR-T cells, while also decreasing the tumor burden and increasing T-cell infiltration relative to CAR-T cells not expressing CXCR2." (PMID 38339310, 2024). "A study using mutant K-ras mouse model of lung cancer showed neutrophil-tumor influx was suppressed upon inhibition of CXCR2 and the diminished neutrophil presence in the tumor was followed by significant tumor reduction." (PMID 38786066, 2024). "It has been shown that pharmacological inhibition of CXCR1 or CXCR2 leads to the promotion of the antitumor T cell response as a consequence of the limited neutrophil tumor infiltration." (PMID 38398111, 2024). "CXCR2 is a chemokine receptor that is involved in various signalling pathways that promote tumour growth, angiogenesis, and metastasis." (PMID 39682746, 2024). "When the CXCR2 blockade was combined with either CSF-1R inhibition or checkpoint blockade, tumor responses were improved." (PMID 39273502, 2024). "In these MC38 tumor models, CXCR2+ myeloid cells were accumulated around the tumors in wild-type C57BL/6 mice." (PMID 38750114, 2024). "Phenotypic PMN profiling using established maturity markers revealed the transition from CD101hi/CXCR2+ mature PMNs in spleen, peripheral blood, and tumor-adjacent tissues to previously reported protumorigenic CD101lo/CXCR2neg TANs." (PMID 38329810, 2024).
tumor (continued). "In the tumor microenvironment, CXCLs/CXCR-2 cascade can signal through RAS/ERK, PI3K/AKT/mTOR, PKC/p38/NF-κB, JAK/STAT3 and PLD to regulate DNA damage, senescence, angiogenesis, survival, proliferation, migration and further administration of chemokines." (PMID 38672477, 2024). "CXCR 1 and CXCR2 CAR-T cells maintain continuous tumor decline and immune memory in various tumor models such as glioblastoma, ovarian cancer, and pancreatic cancer." (PMID 38664743, 2024). "In the context of PCa, IL-8-mediated CXCR2 signalling on cancer cells, ECs, and immune cells enhances these processes, further supporting tumour growth, metastasis, and treatment resistance." (PMID 39199570, 2024). "Altogether, our results demonstrate that low expression of NKX2‐1 fosters tumor growth, and targeting the CXCLs/CXCR2 axis with SB225002 mitigates the tumor growth induced by NKX2‐1 downregulation." (PMID 39113226, 2024). "In summary, CXCR2 CAR-T cell therapy significantly improved CAR-T cell infiltration into tumor tissues and reshaped the cellular composition within the PDAC immune microenvironment, thereby enhancing antitumor effects." (PMID 38430267, 2024). "To dissect the tumor-promoting mechanisms of neutrophils and the tumor-suppressive mechanisms of CXCR2 inhibition, we developed a microphysiological system “NTI-chip” with two independent scenarios, “separated” and “contact”." (PMID 38898176, 2024). "CXCR2 antagonism reduced tumor-infiltrating Gr1+ myeloid cells and greatly increased antitumor efficacy of senescence-inducing agents." (PMID 38786066, 2024). "C-X-C chemokines, by activating the CXCR2, in addition to VEGFA, have been implicated in facilitating tumor angiogenesis." (PMID 38515019, 2024). "Mechanistically, P. anaerobius administration activated integrin α2β1–NF-κB signalling in CRC cells to induce secretion of CXCL1 and recruit CXCR2+ MDSCs into tumours." (PMID 38750176, 2024). "Repertaxin, an inhibitor of IL-8 receptors, CXCR1 and CXCR2, has been reported to reduce tumor proliferation in gastric cancer cell line MKN45." (PMID 39003350, 2024). "Although CXCR2 is expressed on macrophage progenitor cells under tumor conditions, to the best of our knowledge, this is the first study to demonstrate that CXCR2 is expressed on macrophages under non-tumor conditions." (PMID 38351242, 2024). "Based on the results obtained, PTGS2, VEGFA, KDR, CXCR1 and CXCR2 were found to be significantly overexpressed in tumour samples compared to paired normal samples." (PMID 38426619, 2024). "Both MDA-PCa-2b-CXCR1 (5.075 ± 1.284) and MDA-PCa-2b-CXCR2 (5.175 ± 1.162) showed a significant reduction in tumor infiltrating CD45+ cells relative to MDA-PCa-2b-Vec (8.150 ± 1.471)." (PMID 39766038, 2024). "Stimulation of CXCR2 has also been found to induce tumor growth migration, invasion, metastasis, epithelial-to-mesenchymal transition (EMT), and chemoresistance in multiple malignancies." (PMID 39409924, 2024). "Consistently, under the stimulation of heat-killed P. intermedia in our study, the glutamatergic system was downregulated, while the expression levels of CXCL1, CXCL2, and CXCR2 increased and Tregs accumulated in tumor tissues, resulting in tumor progression." (PMID 38515216, 2024). "Significant upregulation of PTGS2, VEGFA, KDR, CXCR1, and CXCR2 expression were observed in tumour samples compared with paired normal samples." (PMID 38426619, 2024). "The genetic ablation of Cxcr2 in mice eliminates tumor accumulation and enhances T-cell infiltration and function." (PMID 38358352, 2024). "Previously, the CXCL1/CXCR2 axis was found to play a key role in promoting MDSCs chemotaxis in the tumor environment." (PMID 38510750, 2024). "We established that suppression of SRGN in LN-18shSRGN cells substantially down-regulates IL-8/CXCR-2 expression and signaling that is active and important in control LN-18shSCR cells to regulate tumor cell functions." (PMID 38672477, 2024).
tumor (continued). "We first characterized the expression patterns of macrophage-relevant chemokines and identified CXCR2 as the key factor regulating T cell trafficking and tumor-specific accumulation in PDAC microenvironment." (PMID 38430267, 2024). "We also determined the effect of CXCR1 and CXCR2 overexpression in tumor growth in nude mice xenografts." (PMID 39766038, 2024). "Tumour tissues exhibited higher median expression levels, except for CXCR2, which showed a higher median expression in normal tissues." (PMID 38426619, 2024). "The results indicated a decline in the number of infiltrated MDSCs in both tumor models from two different cell origins in the CXCR2 CAR-T group compared to the CAR-T group." (PMID 38430267, 2024). "Mice were then treated with CAR-T cells overexpressing CXCR1 or CXCR2, which led to significant tumor regression and appeared to demonstrate a synergy between radiotherapy and chemokine-targeted CAR-T treatment." (PMID 38339310, 2024). "Lastly, CXCR2 expression by DCs induces their migration into the tumor through the CXCL8-CXCR2 axis, since CXCL8, a CXCR2 ligand, is expressed by endothelial cells, tumor-associated macrophages (TAMs), and cancer cells." (PMID 39114657, 2024). "This study showed that the gene expression of IL-17RA, IL-17RC, and CXCR2 in tumor tissues was significantly higher than in normal tissues isolated from patients with BC." (PMID 38515019, 2024). "Further analysis of the cell‐cell interactions indicated communication between tumor cells and neutrophils through CXCLs/CXCR2 signaling activation." (PMID 39113226, 2024). "Our data demonstrated the pivotal role of the CXCLs/CXCR2 signaling in NKX2‐1‐low tumor progression and cancer‐promoting neutrophil infiltration in LUAD." (PMID 39113226, 2024). "PI reshapes tumor-infiltrating CD8+ T cells into more cytotoxic and interferon-activated phenotypes but also increases the infiltration of pro-tumor neutrophils driven by CXCR2." (PMID 39397001, 2024). "It has also been found that CXCL5 promotes tumor angiogenesis in a CXCR2-dependent manner both in vitro and in vivo." (PMID 39835121, 2024). "In our model, the CXCR2 receptor was more expressed in neutrophils from partially irradiated tumors combining LDRT and HDRT, and combining an anti-PD1 treatment to this irradiation scheme further increased the tumor levels of CXCR2+ neutrophils." (PMID 39397001, 2024). "CXCR2 is of particular interest because its primary ligand CXCL8 exerts strong pro-tumor effects through recruitment of myeloid derived suppressor cells (MDSCs), enhancement of angiogenesis and increased tumor metastases." (PMID 38554158, 2024). "Here, we demonstrated that LUAD tumors with NKX2‐1 depletion exhibited increased infiltration of tumor‐promoting neutrophils via the activation of CXCLs/CXCR2 signaling." (PMID 39113226, 2024). "The results demonstrated that the A2AR and CXCR2 inhibitors significantly inhibited tumor growth after treatment." (PMID 38642131, 2024). "The tumor-released EVs induce neutrophil migration toward the tumor microenvironment through the chemokine receptor CXCR2/CXCL8 (IL8) axis, activating the PI3K-AKT pathway in the neutrophils." (PMID 39698539, 2024). "Neutrophils stimulated with GMCSF showed higher levels of both Txnip and Cxcr2 expression suggesting an influence of tumor produced chemokines on neutrophil lineage development." (PMID 38358352, 2024). "Here, we showed that the reduced expression of NKX2‐1 activated CXCLs/CXCR2 signaling, and targeting this pathway resulted in reduced tumor growth." (PMID 39113226, 2024). "The gross necropsy findings showed a remarkable tumor suppression by CXCR2 antagonism compared with the vehicle control recipient mice upon tail vein administration of SB225002 in the subcutaneous mouse model." (PMID 39113226, 2024). "Meanwhile, there is emerging evidence for a tumor-promoting role of CXCR2 in the recruitment of neutrophils and MDSCs toward TME in several types of cancers." (PMID 38750114, 2024).
tumor (continued). "In this study, a significant increase in PTGS2 with VEGFA, KDR, CXCR1 and CXCR2 expression was observed in tumour samples compared to their paired normal samples, with the exception of VEGFB, whose expression was not statistically significant." (PMID 38426619, 2024). "Taken together, these results show that CXCR2 inhibition via AZD-5069 (1 μM) effectively reduces dHL-60 cell migration toward PANC-1 tumor spheroids in the NTI-chip." (PMID 38898176, 2024). "Our results showed that the expression of CXCR2 was significantly upregulated in tumor tissues than in normal tissues." (PMID 38515019, 2024). "Significantly, the treatment of orthotopic Pdxcre, LSL-KrasG12D, and Setd2f/f (KSC) tumors, with a CXCR2 antagonist reduced tumor-infiltrating neutrophiles, but had much less of an effect on tumor-infiltrating macrophages and monocytes." (PMID 38339310, 2024). "Collectively, these findings emphasize that the CXCLs/CXCR2‐dependent mechanism is essential for tumor progression and neutrophil infiltration in NKX2‐1‐low LUAD." (PMID 39113226, 2024). "CXCL5, the ligand of CXCR2, is derived from primary tumor cells, but it is also secreted by immune cells in the TME." (PMID 37142825, 2024). "Intriguingly, the induction of NETosis by tumor‐derived chemokines depends on CXCR1/CXCR2, which regulates leukocyte trafficking toward inflammation and transduces the Gi signaling." (PMID 39015554, 2024). "CXCL5 binds to its receptor, C-X-C motif chemokine receptor 2 (CXCR2), and the CXCL5/CXCR2 axis directly promotes angiogenesis, tumor growth, and metastasis via the ERK/Snail pathway or the AKT/GSK3β/β-catenin pathway." (PMID 39034411, 2024). "The decrease in the percentage of M2 TAMs visible by cytometry was also confirmed by the decrease in CCL17 and CCL22 mRNA (M2 macrophages markers), as well as CXCR2 mRNA in the tumor." (PMID 38504270, 2024). "CXCR1 expression in both MDA-PCa-2b and LNCaP cells inhibited tumor growth; whereas, CXCR2 expression, as previously reported, promoted tumor growth." (PMID 39766038, 2024). "In our study, we found that PTGS2 and VEGF signalling pathway genes (VEGFA, VEGFB, KDR, CXCR1 and CXCR2) were upregulated in OSCC tumour tissues compared to their paired normal tissues." (PMID 38426619, 2024). "Considerable progress has been made in the development of small inhibitors targeting CXCR2, and their potential to effectively inhibit tumor growth in experimental ccRCC has been validated." (PMID 38504270, 2024). "Growth of primary tumor was attenuated in CXCR2 KO mice and, to a greater extent, lung metastasis of LLC was decreased by CXCR2 KO." (PMID 38786066, 2024). "Monitoring the tumor growth in the orthotopic injection model by using the IVIS imaging system also showed the suppression of tumor growth by CXCR2 antagonism." (PMID 39113226, 2024). "This phenomenon led to increased tumor growth, and conversely, tumor growth decreased when inhibited by the CXCR2 antagonist SB225002." (PMID 39113226, 2024). "Although CXCR2 is expressed on other cell types, including epithelial and endothelial cells, inhibitors of CXCR2 mostly impact neutrophils in tumor models." (PMID 37444436, 2023). "While this is decreased from ~ 70% of GFP-positive cells in Braf/Pten/Cxcr2WT tumors, is does indicate that CXCR2 positive tumor cells were present during tumor formation in both genotypes." (PMID 37270599, 2023). "In the current study, we showed that CXCR2 blockade not only reduced RT-induced neutrophilic infiltration but also reduced RT-induced effects on tumor growth and survival of tumor-bearing mice in the RM-9 model." (PMID 38067390, 2023). "A key mechanism for these transcriptional changes involves increased expression of Tfcp2l1, a predicted tumor suppressive transcription factor when Cxcr2 activity is blocked." (PMID 37270599, 2023).
tumor (continued). "Taken together, our data strongly support that CXCR2 is highly and preferentially expressed on neutrophils, which explains the neutrophilic infiltration into the tumor after RT and the reduction thereof upon the CXCR2 blockade." (PMID 38067390, 2023). "Inhibiting the CXCL-CXCR2 axis with CXCR2 antagonists has been shown to inhibit tumor growth, extend survival, and induce anti-angiogenesis effects in tumor xenograft models." (PMID 36986488, 2023). "Based on these results, CXCR2 expression of neutrophil is upregulated in tumor microenvironment, especially in LN+ tumor." (PMID 36670069, 2023). "Genetic ablation of host CXCR2 prevented neutrophil accumulation in pancreatic tumors and led to T cell-dependent tumor growth suppression." (PMID 36942262, 2023). "Using two different syngeneic murine tumor models (RM-9 and MC-38), we demonstrated that CXCR2 blockade significantly reduced RT-induced neutrophilic infiltration." (PMID 38067390, 2023). "In these patients, high expression of CXCL6 and CXCR2 closely correlated with tumor infiltration by M2 macrophages, disease progression, and poor prognosis." (PMID 37509721, 2023). "This study showed that the level of CXCR2 expression was often positively correlated with infiltration of the tumor by DCs, particularly with conventional DCs." (PMID 37686093, 2023). "Of note, CXCR2 antagonist largely reduced tumor‐infiltrating and peripheral neutrophils, but had less effect on tumor‐infiltrating monocytes and macrophages." (PMID 36453584, 2023). "The tumor number per mouse was also reduced upon melanocytic Cxcr2 deletion (0.7 ± 0.9 vs. 2.1 ± 2.3, p < 0.05)." (PMID 37270599, 2023). "CXCR2 was specifically expressed and at high levels by cells clustered as neutrophils, with minimal tumour cell expression." (PMID 37844613, 2023). "Here, using two different syngeneic murine tumor models, we demonstrated that pharmacological blockade of CXCR2 significantly reduced RT-induced neutrophilic infiltration, indicating the critical role of CXCR2 in these processes." (PMID 38067390, 2023). "A significant area of further exploration includes examining all the CXCR1 and CXCR2 downstream pathways elicited by each ligand in the tumor cells." (PMID 36831112, 2023). "The discovery of TAS2R9 as a CAF-selective marker whose targeting can improve the anti-tumor effects of liposomal delivery of a CXCR2 inhibitor opens the door for the modulation of CAF activity as a potent therapeutic strategy in PDAC." (PMID 36986488, 2023). "CXCL1 functions as a chemokine that attracts MDSCs to the tumor microenvironment by signaling via the G protein-coupled chemokine receptor CXCR2." (PMID 37865804, 2023). "Analysis of tumour volumes revealed that DOX enhanced the inhibitory effect of anti-CXCR2 antibody on tumour growth." (PMID 37037815, 2023). "Chronic stress promotes CXCL2/CXCL3 secretion of tumor cells, induces CXCR2 expression of myeloid cells, and thus facilitating spleen myeloid cells movement into tumor tissue through the CXCL2/CXCL3-CXCR2 axis." (PMID 36707854, 2023). "These genes are ligands of CXC chemokine receptor 2 (CXCR2) and known to be involved in angiogenesis in a tumor." (PMID 36928065, 2023). "Optimal CXCR2 suppression by CAF-targeted liposomes was also reflected in its superior constrained tumor growth and reduced cell proliferation." (PMID 36986488, 2023). "This suggests that at our current dosage of SX-682 in the chow, we are unable to achieve complete suppression of CXCR2 at the time of tumor initiation." (PMID 37270599, 2023). "Consistent with the findings in the RM-9 model, CXCR2 blockade selectively reduced RT-induced increase of neutrophils without significantly influencing other myeloid populations in MC-38 tumor grafts." (PMID 38067390, 2023).